IL6 (interleukin 6)
Diseases named in the same sentence as IL6 in open-access papers (continued):
Sharing a sentence is not in itself a finding about the gene and the disease.
alveolitis (17 papers, 2005 to 2025). "Previous studies have suggested that IL-6 leads to inflammation and fibrosis associated with hypersensitivity pneumonitis in mice." (PMID 24736877, 2014). "Mice that are deficient in IL-6 production develop a similar level of alveolitis compared to WT mice however there were differences in the cellular composition of the immune cells recruited into the lung interstitium." (PMID 21699708, 2011). "Numerous studies have reported evidence of a role for IL-6 in inflammatory lung diseases, including hypersensitivity pneumonitis." (PMID 32372213, 2020). "The eight-time exposure of ASD alone (14-week study) deteriorated bronchitis and alveolitis, which accompanied with further increase of cytokines IL-1β, IL-6, IL-12, IL-17A and TNF-α; and chemokines KC, MIP-1α, and RANTES in BALF." (PMID 23731974, 2013). "In our study the significant correlation between IL-6 plasma levels and alveolar score and the higher values of IL-6 found in patients with alveolitis seem to confirm the helpful role of IL-6 as a disease activity index." (PMID 16107215, 2005). "If the skin involvement was excluded from the model IL-6 was seen to be the best independent marker of alveolitis (OR (95%CIs): 6.22 (1.37–38.37))." (PMID 16107215, 2005). "TNF-α promotes inflammatory cell recruitment through regulation of leukocyte and vascular adhesion molecule expression, while IL-6 has been shown to mitigate tissue inflammation in hypersensitivity pneumonitis and reduce lung injury from oxygen toxicity and endotoxin exposure." (PMID 41302046, 2025). "Skin score (>14), skin involvement extent, autoantibodies pattern, FVC (≤ 79%), DLCO (≤ 49%), alveolar score on HRCT (> 6), IL-6 plasma levels (> 0.75 pg/ml) and CRP (> 5 mg/l) were the components of the logistic regression model for alveolitis." (PMID 16107215, 2005). "Nasal inoculation of cotton rats with a recently isolated EV-D68 strain (VANBT/1) significantly upregulated pulmonary cytokine mRNA levels (CCL2, CCL5, CXCL1, CXCL10, IL-6, IFN-β, and IFN-γ) and provided histological evidence of peribronchiolitis and alveolitis." (PMID 34887856, 2021). "Indeed, this herbal medicine can ameliorate pulmonary lesions as it downregulates alveolitis and the Ashcroft score, the underlying mechanism for this might relate to the downregulation of MPO, α-SMA, HYP, collagen I, collagen III, and inflammatory factors (TNF-α, IL-1β, and IL-6)." (PMID 34349830, 2021). "Additionally, males had significantly higher alveolitis, BALF cell numbers, BALF IL-6, and ENA5 autoantibodies than females in the 10 mg dose group." (PMID 29755467, 2018). "IL-6 plasma levels were significantly higher in patients with alveolitis (6.0 ± 10.8 pg/ml) than in patients without (2.4 ± 4.1 pg/ml; p = 0.041)." (PMID 16107215, 2005). "IL-6 plasma levels were higher in patients with alveolitis than in patients without (p = 0.041)." (PMID 16107215, 2005).
Ataxia (17 papers, 2010 to 2025). Ataxia refers to impaired coordination of voluntary muscle movement. "Individuals with this disease have increased levels of the cytokine IL-6 in the cerebrospinal fluid (CSF), astrocyte damage and loss, reactive gliosis, demyelination and can exhibit ataxia and seizures." (PMID 36389783, 2022). "The high levels of IL-6 in the IL-6 tg cerebellum may contribute to the damage and cell loss observed in this brain region at older ages, and consequently the ataxia characteristic of the older IL-6 tg mice." (PMID 25177271, 2014). "Physiologically, chronic exposure of IL-6 has been shown to elicit behavioral abnormalities (seizures and ataxia) and abnormal electro-encephalogram (EEG) patterns in hippocampus." (PMID 40588746, 2025). "This is similar to patients with NMOSD, who have increased intrathecal levels of IL-6, reactive astrogliosis and microgliosis and destructive demyelination and can clinically present with ataxia and seizures." (PMID 35429976, 2022). "By contrast, chronic progressive NB is characterized by intractable slowly progressive dementia, ataxia and dysarthria, with persistent elevation of cerebrospinal fluid (CSF) interleukin 6 (IL-6) activity (more than 20pg/mL)." (PMID 26313435, 2015). "The IL-6 tg mice progressively develop tremor and ataxia by 6 months of age, indicative of cerebellar dysfunction, and infrequently, seizures." (PMID 25177271, 2014). "In contrast, transgenic mice overexpressing IL-6 in glial cells show ataxia, seizures and extensive neurodegeneration." (PMID 20222971, 2010). "The pronounced changes in the cerebellum may be an important factor in the ataxia characteristic of the IL-6 tg mice." (PMID 25177271, 2014). "Transgenic mice that overexpress IL-6 in astrocytes but are otherwise deficient in IL-6 develop a mild form of ataxia, but no symptoms of lymphocyte-driven EAE." (PMID 24023412, 2013). "Concomitant with chronically elevated levels of IL-6 in the CNS, GFAP-IL6 mice exhibit signs of ataxia, neuronal hyperexcitability, and progressive decline in learning function." (PMID 40613088, 2025). "Elevated serum or CSF levels of interleukin-6 (IL-6) and S100B, a marker of astroglial activation and blood-brain barrier (BBB) disruption, were observed in several cases of post-COVID myoclonus and ataxia." (PMID 41404264, 2025). "Mice expressing IL-6 and TNF-a in astrocytes suffer ataxia, inflammation and neurodegeneration after MV infection." (PMID 29312244, 2017). "Also, local microinjection of IL-1β into the cerebellum in vivo produced ataxia, whereas local microinjection of IL-6 did not, suggesting a role for IL-1β in ataxia." (PMID 37950146, 2024).
chronic rhinosinusitis (17 papers, 2016 to 2026). Chronic form of sinusitis. "Systemic inflammation, exemplified by gut dysbiosis, abdominal fat tissue, silicone breast implants, chronic sinusitis, and psychological stress, is associated with elevated levels of interleukin-6 (IL-6), tumor necrosis factor-alpha (TNF-α), and transforming growth factor-beta (TGF-β)." (PMID 40725146, 2025). "Pseudomonas aeruginosa exoproteins, for example, have been shown to disrupt mucosal barriers and increase IL-6 production in asthmatic patients with chronic rhinosinusitis, potentially contributing to mucosal inflammation and exacerbating asthma symptoms." (PMID 41602769, 2026). "All over the world there is very different data describing the IL-6 distribution in cluster analysis of chronic rhinosinusitis." (PMID 34208325, 2021). "FOXA2 is negatively correlated with IL-6 in patients with chronic rhinosinusitis." (PMID 36505412, 2022). "Moreover, reduced expression of the inducible isoform of NO synthase (iNO-synthase) caused by some inflammatory cytokines (IL-4, IL-6, and TGF-β) has been found in the sinus mucosa of chronic rhinosinusitis patients." (PMID 31940834, 2020). "For example, Pseudomonas aeruginosa exoproteins have been shown to disrupt mucosal barriers and increase IL-6 production, potentially contributing to mucosal inflammation in asthmatic patients with chronic rhinosinusitis, which could indirectly influence T-cell differentiation." (PMID 41602769, 2026). "We also found that IL-6 release was reduced with SC79 during exposure to 10% conditioned media from laboratory P. aeruginosa (strain PAO1) and clinical isolates (P11006, L3847, 2338) of P. aeruginosa from chronic rhinosinusitis patients." (PMID 38891035, 2024).
cognitive disorder (17 papers, 2021 to 2026). A disease affects cognitive processes. "Noteworthy, the overexpression of IL‐1, TNF‐α, and IL‐6 mRNA has previously been reported in the hippocampal and cortical brain regions of mice experiencing cognitive diseases." (PMID 38680072, 2024).
Constipation (17 papers, 2020 to 2025). Infrequent or difficult evacuation of feces. "This indicates that the constipation model constructed using loperamide hydrochloride was associated with abnormal levels of the pro-inflammatory cytokines IL-1, IL-6, and IL-8 in the serum." (PMID 37836514, 2023). "The increased mRNA levels of four cytokines, including tumor necrosis factor-α (TNF-α), interleukin (IL)-6, IL-4, and IL-1β, were remarkably recovered in Lop-induced constipation rats after treatment with MPC." (PMID 39857371, 2024). "The serum levels of the pro-inflammatory cytokines IL-1, IL-6, and IL-8 were significantly higher in mice with loperamide hydrochloride-induced constipation than in the control group (p < 0.05)." (PMID 37836514, 2023). "Further study showed that BZYQD intervention reduced the levels of serum inflammatory factors IL-1β and TNF-α and colonic inflammatory factors IL-1β and IL-6 in constipation rats." (PMID 32317976, 2020). "An important factor in the pathogenesis of constipation is the dysfunction of intestinal immunoregulation, and pro-inflammatory factors (IL-1β, IL-6, IL-8, IFN-γ, TNF-α) and anti-inflammatory factor IL-10 are key indicators of the degree of inflammation in the constipation model." (PMID 40718808, 2025). "Thirdly, emerging evidence from experimental research showed that short sleep duration might enhance vulnerability to constipation by altering average levels of inflammatory markers such as interleukin-6 and C-reactive protein." (PMID 36034289, 2022). "Patients with constipation often exhibit abnormalities in the gut-brain axis and dysbiosis of the gut microbiota, which may exacerbate hippocampal damage and memory decline through inflammatory factors such as IL-6 and Tumor Necrosis Factor-alpha (TNF-α)." (PMID 40534737, 2025). "The intestinal expression of IL-6, IL-1β, TNFα, PGE2, and COX-2 were increased in the constipation-induced group, whereas in the groups treated with HLp-nF1 or Dul, they were significantly decreased." (PMID 33872333, 2021). "The levels of IL-1β and IL-6 mRNA were significantly higher in constipation patients (P < .05), while IL-8 mRNA level was no different between the 2 groups." (PMID 35960091, 2022).
contact dermatitis (17 papers, 2013 to 2025). An inflammatory skin condition caused by direct contact between the skin and either an irritating substance or an allergen. "We have previously indicated the anti-inflammatory mechanism associated with IL-6 in an irritant contact dermatitis model." (PMID 34295313, 2021). "We found that participants with skin lesions in form of contact dermatitis caused by chronic exposure to silver and silica nanoparticles had higher genes expression of inflammatory cytokines, including IL4, IL6, IL8, and TNF-α compared to control individuals." (PMID 38454025, 2024). "Together with TNF-α, interleukin (IL)-6 plays a pivotal role in skin inflammation (e.g., contact dermatitis) and hypersensitivity response." (PMID 23710240, 2013). "RT-PCR analyses also revealed mRNA upregulation of pro-inflammatory cytokines (IL-1β and IL-6) and some Th1 or Th2 cytokines (IFNγ, IL-4, and IL-10), but not that of IL-2, TGFβ, and IL-17, at the delayed phase of oxazolone-induced contact dermatitis, similar within the three genotypes." (PMID 36768979, 2023). "Recent studies show that IL-6, IL-1, and TNF-α values are increased in the serum of patients with contact dermatitis, as well as in keratinocyte cell culture." (PMID 40141696, 2025). "They found that CA has anti-inflammatory activities in both acute and chronic contact dermatitis models through blocking of mRNA and protein synthesis of the cytokines, such as TNF-α, IL-6, and IL-1β, and neutrophil-mediated myeloperoxidase activity." (PMID 34040528, 2021). "As shown in previous studies, C. pepo L. extract applied topically and orally in rats with contact dermatitis and chronic stress demonstrated a significant reduction in TNF-α and IL-6 levels, both systemically and locally in the skin, which was accompanied by a reduction in iNOS and COX-2." (PMID 41157100, 2025). "A mouse model of contact dermatitis showed that black garlic decreased the activation of macrophages, as well as the release of inflammatory mediators like nitric oxide II (NO), tumor necrosis factor (TNF-α), and interleukin 6 (IL-6)." (PMID 38339077, 2024). "In a mouse model of irritant contact dermatitis induced by croton oil, topically applied recombinant human TRX significantly suppressed the inflammatory response by inhibiting the production of cytokines and chemokines, such as Tnf-α, Il-1β, Il-6, Cxcl1, and Mcp-1, in the skin tissues." (PMID 32244938, 2020). "An in vivo experiment of irritant contact dermatitis (ICD) in mice induced by TPA showed that NCEUG reduced significantly the ear edema in mice when compared to the EUG solution, as well as the leukocyte infiltration and IL-6 level, possibly due to better skin permeation and irritancy blockage." (PMID 30647816, 2018).
diabetic foot ulcers (17 papers, 2010 to 2025). "In patients with diabetic foot this "adipo-vascular axis"expression in lower plasma levels of adiponectin and higher plasma levels of IL-6 could be linked to foot ulcers pathogenesis by microvascular and inflammatory mechanisms." (PMID 20836881, 2010). "Persistently elevated levels of proinflammatory cytokines such as IL-6, IL-1β, IL-8 and TNFα have been found in the wound bed fluids of patients with diabetic foot ulcers." (PMID 39941031, 2025). "In addition, TNF-α, IL-6, and IL-1β levels have been revealed to return to normal levels by propolis administration, and infections in diabetic foot ulcers have been proven to improve." (PMID 37542207, 2023). "Likewise, dracorhodin (a flavonoid from Dragon’s Blood) improved DFU outcomes via multi-pathway modulation: it dose-dependently enhanced collagen deposition and angiogenesis while reducing inflammatory cytokines (TNF-α, IL-6) and ROS levels in a diabetic foot ulcer model." (PMID 40728954, 2025). "However, the available data suggest that IL-6, CRP, and TNF-α measurements in diabetic foot ulcers could be valuable tools for patient risk stratification, as well as predictors for lower-limb amputation and perioperative risk of morbidity and mortality." (PMID 39596058, 2024). "This study aimed to assess how negative pressure occlusion drainage combined with silver ion dressing affects inflammatory cytokine levels (IL-6, TNF-α) and wound healing in patients with diabetic foot ulcer." (PMID 41393293, 2025). "Increased serum levels of IL-10, IL-6, IFN-γ, IL-4 and adiponectin have been shown in patients with diabetic foot ulcers treated with hyperbaric oxygen." (PMID 36198698, 2022). "Real-Time Polymerase Chain Reaction: RT-PCR for the gene expression of CD68, CD86, CD206, CD40, IL-6, IL-1β, and TNF-α revealed increased relative gene expression (normalized to housekeeping gene 18S) in diabetic foot ulcer tissues compared to control tissues." (PMID 36362563, 2022). "Silver dressings enhance wound healing without toxicity and promote healing in diabetic foot ulcers by regulating inflammatory factors like IL-6 and TNF-α." (PMID 41393293, 2025). "A previous study conducted by our group reported that in comparison to diabetics without diabetic foot, subjects with diabetic foot had higher IL-6 and resitin plasma levels, and lower adiponectin plasma levels." (PMID 28056981, 2017). "Our group reported that compared to diabetics without diabetic foot, diabetic subjects with diabetic foot had higher IL-6 and resistin plasma levels, and lower adiponectin plasma levels, as possible determinants of higher cardiovascular risk." (PMID 28056981, 2017). "In addition to their role in PDN, IL-6 and TNF-α may also contribute to the pathogenesis of diabetic foot ulcers." (PMID 39596058, 2024).
dyslipidaemia (17 papers, 2012 to 2024). "Specifically, adiponectin can have beneficial effects on lipid metabolism because of its insulin-sensitizing effects, whereas IL-6 has been involved in the dysregulation of insulin signalling and has been associated with dyslipidaemia." (PMID 27567677, 2016). "Dyslipidaemia can induce the production of inflammatory cytokines, such as interleukin-6 and tumour necrosis factor-α, and reduce the anti- inflammatory cytokines, such as Interleukin-10." (PMID 31752704, 2019). "Since tumour‐induced IL6 can induce dyslipidaemia, we next investigated the role of systemic IL6 on host lipid metabolism in our models." (PMID 29540470, 2018). "Consistent with this, systemic IL6 also stimulates hepatic cholesterol biosynthesis in mice with CRPC leading to dyslipidaemia with elevated levels of circulating cholesterol." (PMID 29540470, 2018). "IL-6 and interleukin 6 signal transducer (IL6ST) have been identified as dyslipidaemia susceptibility loci." (PMID 30157878, 2018). "In addition, systemic inflammation has been proposed to be accompanied by dyslipidaemia, producing several proinflammatory factors (including tumour necrosis factor (TNF)-α and interleukin 6 (IL-6))." (PMID 26264374, 2015). "Furthermore, HOMA-IR index and serum cytokine levels (IL-6 and TNF-α) involved in dyslipidaemia were improved, and no toxicity appeared." (PMID 26264374, 2015).
hyperandrogenism (17 papers, 2011 to 2026). Excessive secretion of androgens from the adrenal glands or gonads. "While IL-6 plays a dual role (both pro- and anti-inflammatory), IL-1β is strictly pro-inflammatory, leading to ovarian inflammation and androgen excess." (PMID 40385768, 2025). "These immune cells release inflammatory cytokines, such as tumor necrosis factor-alpha (TNF-α), interleukin-6 (IL-6), and interleukin-1β (IL-1β), which impair insulin signaling and exacerbate androgen excess." (PMID 41382225, 2025). "Among interleukins, IL-6 acts as a pro-inflammatory cytokine, and the production of the IL-6-producing T cells, neutrophils, and M1 macrophages is strongly correlated with hyperandrogenism." (PMID 38540173, 2024). "Compared to IL-6 and TNF-α, IL-1β has a more localised impact on ovarian dysfunction and hyperandrogenism." (PMID 40385768, 2025). "Further, hyperandrogenism in PCOS also elevates inflammatory markers such as interleukin (IL)−22, IL-1, and IL-6." (PMID 40790236, 2025). "The current study observed a notably upregulated expression of TNF-α, IL-6 as well as NF-κB in the PCOS group, which was accompanied with metabolic disturbances and hyperandrogenism." (PMID 38589892, 2024). "A large body of evidence has shown that hyperandrogenism in PCOS patients is closely related to inflammation-related genes such as TNF-α, Tnf receptor 2 (TNFR2) and IL-6." (PMID 39453929, 2024). "Hormonally, LP suppressed hyperandrogenism, as evidenced by decreased testosterone, while rebalancing inflammatory mediators through IL-10 upregulation and concomitant reduction of TNF-α, IL-6, IL-1β, and MCP-1." (PMID 41624200, 2026). "Hyperandrogenism in PCOS promotes increased production of the IL-6-producing Th1 cells, neutrophils, and M1 macrophages; because of the resultant increase in IL-6 concentration, there is increased activation of the AKT pathway, which contributes to two features of PCOS." (PMID 37062827, 2023). "Hyperandrogenism in PCOS affects immune cells in different ways, but their key function in PCOS is the production of a wide range of cytokines, including TNF-ɑ, IL-1, IL-6, and IL-22." (PMID 37062827, 2023).